IFNG (interferon gamma)
Diseases named in the same sentence as IFNG in open-access papers (continued):
Sharing a sentence is not in itself a finding about the gene and the disease.
Insulin resistance (continued). "This research was conducted to investigate if there is a relation between insulin resistance incidence and inhibition of interferon gamma production or not." (PMID 27642351, 2016). "Obesity increased MHCII expression in adipocytes, while deletion of MHCII specifically in adipocytes (aMHCII−/−) led to a decrease of adipose IFNγ expression, an increase of VAT Treg cell abundance and reduced insulin resistance without any changes in weight gain in obese mice." (PMID 30323806, 2018).
lymphoma (144 papers, 2007 to 2026). A malignant (clonal) proliferation of B- lymphocytes or T- lymphocytes which involves the lymph nodes, bone marrow and/or extranodal sites. "For IFNG, we analyzed the expressions in 26 lymphoma patients, which included the rs2069718 polymorphisms of 13 AA, 12 AG, and 1 GG." (PMID 37329186, 2023). "Univariate Cox proportional hazards regression model showed that the frequency of rs2069718 genotype of IFNG was significantly associated with the survival of lymphoma patients under dominant, codominant, additive and allele models (all p < 0.05)." (PMID 37329186, 2023). "Our results showed that IFNG rs2069718 was associated with the survival of lymphoma patients under dominant model, and the G allele of rs2069718 had a lower OS." (PMID 37329186, 2023). "Especially, IFNG rs2069718 and IL‐12A rs6887695 were significantly associated with OS, and the mRNA expressions of the two genes were also associated with OS of lymphoma patients." (PMID 37329186, 2023). "We have previously reported that post-transplant lymphoma patients have an acquired deficiency of signal transducer and activator of transcription 4, which results in defective IFNγ production during clinical immunotherapy." (PMID 24363024, 2014). "Mice deficient in IFNγ develop sarcomas or lymphomas more frequently than WT animals." (PMID 40287766, 2025). "Therefore, we identified that the SNPs associated with lymphoma patients' survival were the rs2069718 of IFNG and the rs6887695 of IL12A." (PMID 37329186, 2023). "The prediction of in situ lymphoma development was associated with higher IFNγ expression." (PMID 29293620, 2018). "Although effects of Tfh1 infiltration of lymphomas are difficult to predict they could be associated with elevated circulating levels of IFNγ, and this could be explored as a biomarker." (PMID 29293620, 2018). "Therefore, in order to further determine the role of the two genetic polymorphisms on the progression and prognosis of lymphoma, we explored the association of the two genetic polymorphisms and the mRNA expression levels of IFNG and IL12A in some available lymphoma samples." (PMID 37329186, 2023). "Thus, incorporating lunasin into cytokine-based treatment may rescue the production of IFNγ by NK cells from heavily treated lymphoma patients with acquired STAT4 deficiency." (PMID 24363024, 2014). "Previous CD19 CAR T cell studies in lymphoma demonstrated a significant association between CRS/ICANS and elevated levels of cytokines, including IFNγ, IL-2, IL-6, IL-8, IL-10, IL-15, and TNFα1,20–22." (PMID 39011120, 2024). "In detail, the anti-lymphoma activity of CAR.CD19-T cells was tested in long-term co-culture assays with CD19+ lymphoma Daudi and Raji cell lines, either in the absence or in the presence of the anti-IFNγ mAb emapalumab." (PMID 37296093, 2023). "The results of statistical analysis in our research found that rs2069718 of IFNG and rs6887695 of IL12A were significantly associated with OS in lymphoma patients." (PMID 37329186, 2023). "And in the dominant model, the expression level of IFNG in lymphoma patients with AG/GG genotype was also higher than those with AA genotype (p = 0.0284)." (PMID 37329186, 2023). "In terms of potential clinical implications, the IFNγ/IFNα mRNA ratio in salivary gland tissue was shown to have the best discriminative capacity for lymphoma development in patients with pSS." (PMID 35892673, 2022). "Modulating HSP90 was found to affect the NK cell degranulation response and IFNγ production in lymphoma patients." (PMID 35572591, 2022). "Here we employed an integrated genomic and proteomic antigen discovery strategy aimed at measuring how interferon gamma (IFN-γ) alters antigen presentation, using a human lymphoma cell line, GRANTA-519." (PMID 33936100, 2021).
lymphoma (continued). "In these DLBCL tumors, increased IFNγ expression by CD8 T cells similarly correlated with slow-growing lymphomas, consistent with reports showing upregulation of MHC genes by IFNγ responsive genes and increased tumor response." (PMID 33854497, 2021). "We observed that CD20-TCB mediated lymphoma/T cell can trigger the production of IFNγ, which in turn leads to production of CXCL10." (PMID 33406104, 2021). "After tumor regression, T cells from treated animals were able maintain the ability to produce IFNγ and acquired immunological memory to rapidly reject A20 lymphoma rechallenges." (PMID 31307539, 2019). "RBPJ-deficient splenic NKp46+NK1.1+ cells showed significantly increased lytic abilities on YAC-1 mouse lymphoma cells that correlated with an increase frequency of cells capable to produce TNFa and IFNg." (PMID 29930552, 2018). "Ixazomib sensitivity in DLBCL cells is correlated with immunoproteasomal activity; stimulating lymphoma cells with interferon gamma induced immunoproteasome activity and sensitized these cells to ixazomib." (PMID 29416618, 2018). "Two groups have recently reported that, C/EBPβ plays an essential role in limiting proliferation of CD4+ T cells and IFNγ production in the case of lymphoma-educated DCs and Gr1+CD11b MDSC." (PMID 30544623, 2018). "There has been little work in this area but one prospective study showed that IFNγ levels (together with levels of IL-2 and ICAM) associate with the risk of developing lymphoma." (PMID 29293620, 2018). "Our data show that lymphoma cell lines were the least affected by IFNγ in terms of NK cell ligand expression." (PMID 28428785, 2017). "To confirm this, we measured the ability of the spleen cells to produce interferon gamma (IFNγ) from A20 inoculated lymphoma bearing mice with different treatments." (PMID 26181041, 2015). "The combination of lunasin and cytokines (IL-12 plus IL-2) was capable of restoring IFNγ production by NK cells from post-transplant lymphoma patients." (PMID 24363024, 2014). "This primarily occurs because cytokines (such as interleukin-6, interferon-gamma, etc) secreted by lymphoma lead to a hyperinflammatory state, which may contribute to the development of HLH." (PMID 41559979, 2026). "In lymphoma patients, traditional gating analysis also revealed a moderate direct correlation between the representation of naïve T cells and the magnitude of anti-spike IgG, and IFNg." (PMID 40630518, 2025). "Combinatory treatment with CpG-Stat3 siRNA and CTLA4 antibody in A20 lymphoma tumor-bearing mice significantly increased the percentages of IFNγ and/or granzyme B (GZMB) producing CD4+ T cells and CD8+ T cells in tumors compared to either CpG-Stat3 siRNA or CTLA4 antibody alone." (PMID 39618825, 2024). "Taking into account that anti-PD-1 immunotherapy may affect HSP90 expression in NK cells, we assessed the effect of HSP90 downregulation on the degranulation response, granzyme B and IFNγ production in NK cells of lymphoma patients." (PMID 35572591, 2022). "Nevertheless, CD4+ T-helper cells from αDEC205-BZLF1 expressed the T-helper 1 phenotype (Tbet+ and IFNγ+) which might be supportive of lymphoma prevention and favorable outcome." (PMID 34073261, 2021). "Our data is compatible with this literature and suggests the idea that Tfh1 cells might be present in the microenvironment of low grade B-cell lymphomas and that in vivo IFNγ might be required for maintenance or proliferation of the lymphoma cells." (PMID 29293620, 2018). "In light of this finding and the marked defects in the in vitro capacity to degranulate and produce IFNγ, it was surprising that WASp KO NK cells could control growth of lymphoma cells such as A20, YAC-1, and RMA-S cells in vivo." (PMID 27477778, 2016).
lymphoma (continued). "This probiotic is also able to reduce the mortality of animals challenged with a lethal dose of the murine LBC lymphoma cells, triggering mechanisms that include the generation of a Th1 response characterized by a high production of IL-12 and interferon-gamma (IFNγ)." (PMID 25978357, 2015). "Notably, the combination of lunasin and cytokines is capable of rescuing IFNγ production by NK cells from heavily treated lymphoma patients who are immune compromised." (PMID 24363024, 2014). "Similarly, combinatory treatments with CpG-Stat3 siRNA and PD-1 antibody in A20 lymphoma tumor-bearing mice led to significantly higher percentages of activated CD8+ T cells positive for IFNγ, CD107α, which measures T cell cytotoxicity, and GZMB at the tumor sites." (PMID 39618825, 2024). "More importantly, the IFNG (rs2069718) and IL12A (rs6887695) were associated with the overall survival (OS) of lymphoma patients remarkably, and the adverse effects of GC genotypes could not be offset by Bonferroni correction for multiple comparison in rs6887695 especially." (PMID 37329186, 2023). "Besides, systems biology transcriptomic analyses of flow-sorted lymphoma cells co-cultured with CD19-CAR-NK92 cells revealed activation of important pathways involved in lymphoma cells: IFNγ signaling, apoptosis mechanisms, ligand binding, and immunoregulatory and chemokine signaling pathways." (PMID 33752707, 2021). "Selinexor pre-treatment of lymphoma cells significantly increased NK cell mediated cytotoxicity against SU-DHL-4, JeKo-1 and Ramos cells, concurrent with increased CD107a and IFNγ expression on NK cells." (PMID 34926302, 2021). "The expression of PARP9 was shown to be induced by IFNγ, which is also triggered by IAV, and expression of PARP9 in lymphoma cells was found to increase the expression of several interferon-stimulated genes." (PMID 29980615, 2018). "IFNγ production by T-cells is stimulated by BAFF and it is, therefore, conceivable that IFNγ and BAFF act together to promote lymphoma proliferation." (PMID 29293620, 2018). "In summary, the magnitude of SARS-CoV-2-specific memory T cells capable of mounting IFNg responses in lymphoma patients was not differentially influenced by the type of cancer treatment." (PMID 40630518, 2025). "Here authors show in a humanized mouse model that blocking IFNγ with the monoclonal antibody emapalumab mitigates the adverse effects of CAR.CD19-T cells without compromising their anti-lymphoma efficacy." (PMID 37296093, 2023). "LASSO regression and univariate Cox regression indicated that the rs2069718 of IFNG and rs6887695 of IL12A were correlated with the survival of the lymphoma patients under dominant and codominant models (all p < 0.05), and the AUC (Area Under Curve) were all greater than 0.62." (PMID 37329186, 2023). "The downregulation of IFNG is not necessarily inconsistent with the observed effect of increased NK cell ADCC against lymphoma." (PMID 37630689, 2023). "They found that chronic treatment with the non-selective β-agonist isoprenaline promoted lymphoma development and significantly suppressed the proliferation, interferon gamma (IFNγ) production, and cytolytic killing capacity of antigen-specific CD8+ T cells." (PMID 33114769, 2020). "However, ICAM-1 upregulation exceeded MHC-class I upregulation (ratio <1) in the EWS cell lines CHLA-9 and CHLA-10 and the lymphoma cell line Ramos-RA1, for which IFNγ treatment resulted in decreased NK cell-mediated lysis." (PMID 28428785, 2017). "Notably, 60% of patients (3 out of 5) who relapsed from lymphoma during this period failed to generate vaccine-induced IFNγ responses." (PMID 40630518, 2025). "Regarding possible triggers, lymphoma-complicated CLS patients have elevated levels of various cytokines, such as granulocyte colony-stimulating factor (G-CSF), interleukin-6 (IL-6), interleukin-10 (IL-10), interferon-gamma (IFN-γ) and tumor necrosis factor alpha (TNF-α)." (PMID 39072323, 2024).
lymphoma (continued). "Importantly, our in vitro and in vivo experiments show that IFNγ inhibition does not affect the ability of CD19-targeting CAR-T (CAR.CD19-T) cells to eradicate CD19+ lymphoma cells." (PMID 37296093, 2023). "In addition, we observed co-expression of immune mediators, such as interferons and their targets (IFNA1-2, IFNA7-8, IFNB1, and IFNG), as well as proinflammatory cytokines (IL-1B and IL12B) and chemokines and their receptors (CXCL9-11 and CXCR3) by CpG(B)-STAT3dODN-treated lymphoma cells (right)." (PMID 29433938, 2018). "In addition, restimulation of splenocytes from lymphoma surviving mice with a murine fibrosarcoma cell line, stably transfected to express human c-MYC (MCA205MYC-tet), also resulted in a significantly higher IFNγ secretion compared to untransfected MCA205 cells." (PMID 24130880, 2013). "When 2.5x105 spleen cells were incubated with 1x104 291PC lymphoma cells (E:T ratio 0.08-0.23:1 with respect to multimer-binding CD8+ T-cells), we did not observe any secretion of IFNγ although these cells express human c-MYC." (PMID 24130880, 2013).
atopic dermatitis (142 papers, 1993 to 2026). "Dysregulated IFNγ-mediated T helper 1 (Th1) responses are associated with a shift from balanced Th1/Th2 immune responses toward a Th2 cell-dominated profile in atopic dermatitis (AD)." (PMID 37570749, 2023). "Avène spring water, as a mineralized water, has shown proliferative effects in lymphocytes isolated from atopic dermatitis (AD) patients, along with increases in Th1 cytokines (IFNγ and IL2) and reductions in Th2 cytokines." (PMID 38921545, 2024). "Patients with atopic dermatitis have a cytokine profile characterised by abnormal levels of interleukins 4, 12, 13, 18, 22, 31 and 33; thymic stromal lymphopoietin; and interferon gamma." (PMID 35582626, 2022). "Atopic dermatitis increased the expression levels of IL-4, IL-13, IL-6, IL-17, IFNγ, and TNFα but decreased the expression of IL-10 in BALB/c mouse, in an SOCS1-dependent manner." (PMID 30459600, 2018). "In addition, the upregulation of interferon gamma expression in atopic dermatitis downregulates the epidermal synthesis of ceramides." (PMID 30608955, 2019). "The antioxidant and anti-inflammatory effects of water extracts of maqui berry were tested in a mouse dermatitis model showing an increase of interferon-gamma (IFN-γ) levels and a decrease of interleukin-4 (IL-4), suggesting its potential use for atopic dermatitis treatment." (PMID 31357475, 2019). "A randomised, double-blind, placebo-controlled trial showed that recombinant interferon-gamma (rIFN-gamma) given by daily subcutaneous injection over 12 weeks in patients with moderate to severe atopic dermatitis was well tolerated and capable of producing significant clinical improvement." (PMID 24276125, 2013). "In our previous studies, we showed that intramuscular administration of autologous total IgG could induce significant clinical improvements and increases of the serum levels of interleukin-10 (IL-10) and interferon-gamma (IFN-γ) in patients with atopic dermatitis." (PMID 35665739, 2022). "Vα7.2+/CD161− T cells in atopic dermatitis exhibited a decrease in CD8 and IFNγ-producing subsets but an increase in CD38 activated and IL-22-producing subsets." (PMID 38542456, 2024). "As expected, the established gene signature for AD (meta-analysis-derived atopic dermatitis (MADAD)) was significantly enriched in the lesional skin biopsies of both the high (p = 0.0005) and low (p = 0.0004) IFNG groups, with a tendency towards greater enrichment in the high IFNG group." (PMID 38892346, 2024). "FDK primary cultures (atopic dermatitis, n = 11; non-atopic controls, n = 7) before and after interferon gamma (IFN-γ) treatment were used for microarray analysis and quantitative RT-PCR." (PMID 23385231, 2013). "In conclusion, using mice and ovalbumin mimicking allergic dermatitis and using IBH, a natural equine skin allergic disease, we demonstrated that IL‐5 vaccination significantly decreased allergen‐specific IgE levels, together with Th1/Th2 cytokines, such as IL‐4 and IFNγ." (PMID 40838325, 2025). "Importantly, in an atopic dermatitis-like cell model induced by TNFα/IFNγ, LF216EV significantly modulated the expression of immune regulatory genes (TSLP, TNFα, IL-6, IL-1β, and MDC), indicating its potential functionality in atopic dermatitis." (PMID 40028723, 2025). "In contrast we could not observe Th2 cells producing IL-17 or IFNγ which is different from the data found in allergic asthma and atopic dermatitis patients." (PMID 24911279, 2014). "The IFNG and IL5 methylation rates were higher among exclusively breastfed infants with atopic dermatitis compared to the non-breastfed." (PMID 37520545, 2023).